IQGAP3 (IQ motif containing GTPase activating protein 3)
Diseases named in the same sentence as IQGAP3 in open-access papers (continued):
Sharing a sentence is not in itself a finding about the gene and the disease.
psoriasis (1 paper, 2024). An autoimmune condition characterized by red, well-delineated plaques with silvery scales that are usually on the extensor surfaces and scalp. "By conducting transcriptome profiling of HaCaT keratinocytes, we identified numerous psoriasis-associated pathways that were affected when IQGAP3 was knocked down." (PMID 38674130, 2024). "To identify the cytokine-induced pathways affected by IQGAP3 knockdown and relevant to psoriasis, we conducted a manual analysis." (PMID 38674130, 2024). "This research aims to investigate the role of IQGAP3 in the development of the psoriatic phenotype in keratinocytes and to explore its potential as a therapeutic target for psoriasis treatment." (PMID 38674130, 2024). "This suggests that IQGAP3 knockdown in the skin can be a promising strategy for correcting the excessive proliferation of keratinocytes in psoriasis." (PMID 38674130, 2024). "Previous research has shown that IQGAP3 is overexpressed in the skin of patients with psoriasis." (PMID 38674130, 2024). "Given the multitude and diversity of pathways regulated by IQGAP3 in keratinocytes, targeting this protein for therapeutic inhibition may not be the most effective strategy to normalize the phenotype of keratinocytes is psoriasis." (PMID 38674130, 2024). "IQGAP3 knockdown inhibited EGFR signaling, which plays a crucial role in epidermal homeostasis and regulation of skin inflammatory responses and has elevated expression in active epidermal lesions of psoriasis." (PMID 38674130, 2024). "This conclusion is also based on the diversity and number of pathways mediated by IQGAP3, indicating that targeting this protein alone is not sufficient to address the complex pathogenesis of psoriasis." (PMID 38674130, 2024). "Despite these significant findings, the diversity of the alterations observed in the knockdown cells led us to conclude that IQGAP3 may not be the best target for the therapeutic inhibition to normalize the phenotype of keratinocytes in psoriasis." (PMID 38674130, 2024).
renal cell carcinoma (1 paper, 2022). "The highly expressed IQGAP3 in multiple subtypes of renal cell carcinoma has a clear prognostic value." (PMID 36275458, 2022). "The expression of IQGAP3 in renal cell carcinoma, its correlation with prognosis or chemoradiotherapy sensitivity, the molecular mechanism involved in tumor malignant progression will help further biomarkers identification and combination therapy exploration." (PMID 36275458, 2022). "All the three subtypes of renal cell carcinoma showed significantly enhanced IQGAP3 expression in tumor tissues than that in normal tissues." (PMID 36275458, 2022). "In this work, IQGAP3 was overexpressed not only in many tumor types, but also in the three common subtypes of renal cell carcinoma." (PMID 36275458, 2022). "This suggests that IQGAP3 has good prognostic value in renal cell carcinoma and inhibitors of IQGAP3 function may prevent tumor invasion, proliferation and migration." (PMID 36275458, 2022).
skin cancer (1 paper, 2024). "Previously, we have found IQGAP3 to be the only member of this family overexpressed in lesional psoriatic skin, and Monteleon and colleagues have found IQGAP3 to be a promising target for skin cancer." (PMID 38674130, 2024).
tumor (41 papers, 2006 to 2025). "High mRNA expression of IQGAP3 was associated with tumor mutational burden, microsatellite instability, immune cell infiltration, and immune modulators." (PMID 35274003, 2022). "IQGAP3 can not only regulate tumor 3D growth, but also cause drug resistance by stabilizing the genome and reducing the accumulation of DNA damage during radiotherapy and chemotherapy." (PMID 36275458, 2022). "It was found that IQGAP3 is associated with a variety of tumor immune cells, especially CD4 Th2 cells and MDSCs cells in almost all tumors; however, the relationship with the immune infiltration of CD4 Th1 cells is not obvious." (PMID 36164370, 2022). "Microsatellite instability (MSI), immune checkpoints, mismatch repair (MMR), and tumor mutational burden (TMB) all closely interacted with IQGAP3 mRNA." (PMID 36164370, 2022). "IQGAP3 expression was closely associated with tumor mutational burden (TMB), microsatellite instability (MSI), infiltration of immune cells, and immune modulators." (PMID 35274003, 2022). "Their results showed that IQGAP3/BMP4 overexpression was observed in higher-stage and higher-grade diseases with high risks of recurrence and progression, whereas IQGAP3/FAM107A overexpression was associated with larger tumor size and disease progression." (PMID 33672869, 2021). "In summary, as a novel tumor marker, IQGAP3 has a better diagnostic efficacy than B7-H4 and COX-2 in detecting CRC." (PMID 31223291, 2019). "Further analysis of IQGAP3, with respect to tumor invasiveness and grade also yielded a high diagnostic accuracy, suggesting that IQGAP3 can be used to discriminate BC from non-BC patients with hematuria." (PMID 30245975, 2018). "Notably, results showed that tumor grade (p = 0.010) and IQGAP3/BMP4 (p = 0.004) were independent risk factors for progression." (PMID 38668066, 2024). "IQGAP3 is associated with tumor treatment response and tolerance in other types of tumors." (PMID 37370891, 2023). "Increased IQGAP3 expression was associated with a higher tumor stage and shorter overall survival." (PMID 36831467, 2023). "Our results showed that high IQGAP3 expression was associated with tumor OS, DSS, DFI, or PFI." (PMID 36164370, 2022). "Immunohistochemical data were obtained from Human Protein Atlas (HPA) to assess IQGAP3 protein expression differences, and exome data from TCGA were used to analyze IQGAP3 expression in relation to tumor mutational burden (TMB), microsatellite instability (MSI), and mutation." (PMID 36164370, 2022). "Positive IQGAP3 expression was significantly associated with poor tumor differentiation." (PMID 36320006, 2022). "Meanwhile, IQGAP3 has been found to be positively correlated with the infiltration of B cells, macrophages, and dendritic cells, indicating its potential role as a tumor-specific antigen." (PMID 40361412, 2025). "To further confirm the important role played by IQGAP3 in GC, we created a tumor model using nude mice in vivo." (PMID 41446602, 2025). "The TCGA database revealed that IQGAP3 expression was higher in tumor tissue than in normal tissue (P < 0.001)." (PMID 41446602, 2025). "In vivo, tumor growth and M0 macrophage infiltration were both suppressed in the group with low IQGAP3 expression." (PMID 41446602, 2025). "IQGAP3 is a critical regulator of GC that promotes tumor proliferation, clonogenicity, and invasive ability." (PMID 41446602, 2025). "In the IQGAP family, the expression of IQGAP2 is reduced and acts as a tumor suppressor in most solid cancer types, while IQGAP3 is overexpressed and functions as an oncogene." (PMID 40361412, 2025). "In vivo experiments demonstrated that low IQGAP3 expression significantly reduced tumor growth (P < 0.05)." (PMID 41446602, 2025). "The paired difference analysis of IQGAP3 expression levels in normal and tumor tissues revealed similar upregulation of IQGAP3 expression in tumor tissues (P < 0.001)." (PMID 41446602, 2025).
tumor (continued). "IQGAP3+ tumor cells were predominantly enriched in cell cycle and mitosis, indicating their proliferating potential." (PMID 39685635, 2024). "In BC diagnosis, the significance of IQGAP3 increases with tumor grade, with AUC values of 0.805, 0.915, and 0.929 for G1, G2, and G3 tumor grades, respectively." (PMID 39295845, 2024). "IQGAP2 expression is reduced and plays a tumor suppressor role in most solid cancer types, while IQGAP3 is overexpressed and acts as an oncogene." (PMID 36831467, 2023). "IQGAP3 was expressed in tumor cells, T cells, and monocytes, while WASIR1 was primarily expressed in mast cells." (PMID 37370891, 2023). "IQGAP2 expression is reduced and plays a tumor suppressor role in most solid cancer types, while IQGAP3 is overexpressed and acts as an oncogene in the same cancer types." (PMID 36831467, 2023). "Further analysis at the protein level confirmed that KIF4A and IQGAP3 were upregulated in tumor tissues instead of normal tissues from the HPA database." (PMID 37370891, 2023). "First, the expression of IQGAP3 was compared between tumor and normal samples in TCGA database using TMER2." (PMID 36164370, 2022). "IQGAP3 is involved in various tumor pathways, including MAPK signaling pathway, Ras signaling pathway, and TGF-β/Smad signaling pathway." (PMID 36164370, 2022). "Immunohistochemistry staining of IQGAP3 showed that it was very weakly expressed in the cytoplasm of normal liver tissues and strongly expressed in the cytoplasm of tumor tissues." (PMID 36320006, 2022). "To further understand the role of IQGAP3 in tumor immunity, we evaluated the correlation between IQGAP3 expression and various immune cells." (PMID 36164370, 2022). "To further understand the role of IQGPA3 in tumor immunity, we explored the relationship between IQGAP3 mRNA expression levels with immune cell infiltration through the TIMER2 database." (PMID 36164370, 2022). "The high expression of IQGAP3 was correlated with tumor stage, lymph node metastasis, and a poor prognosis in diverse types of human cancer." (PMID 35274003, 2022). "The further excavation of the function of IQGAP3 in DNA damage repair is the embodiment of the application of the concept of synthetic lethality in tumor treatment, which will help to guide the clinical practice of precise individual treatment." (PMID 36275458, 2022). "IQGAP3 regulates DNA synthesis and mitosis in HepG2 cells and promotes cell proliferation and tumor growth in mice." (PMID 36320006, 2022). "The mRNA sequencing data of IQGAP3 from 730 adjacent normal tissues and 10,363 tumor tissues in TCGA pan cancer database were extracted." (PMID 36275458, 2022). "We further explored the levels of IQGAP3 methylation in normal and tumor tissues and found that IQGAP3 methylation levels were decreased and statistically significant in 7 tumors." (PMID 36164370, 2022). "Taken together, IQGAP3 likely affects tumor initiation and progression by affecting cell cycle, cellular senescence, and immune-related pathways." (PMID 36164370, 2022). "According to clinical features in TCGA database, the higher the TNM (tumor-node-metastasis) stage, histological grade and pathological stage, the higher IQGAP3 expression in KIRC and KIRP." (PMID 36275458, 2022). "The possible role of IQGAP3 in tumors is related to tumor types, and the mechanism research is still in the initial stage." (PMID 36275458, 2022). "The high expression of IQGAP3 promotes malignant processes such as tumor growth and invasion with different downstream signal pathways in many types of tumors, and recent studies have found that it is related to the treatment outcome." (PMID 36275458, 2022). "Immunohistochemistry also showed that the expression of IQGAP3 was high in tumor tissues, which is consistent with the analysis of the database." (PMID 36275458, 2022).
tumor (continued). "Third, the significance of IQGAP3 in tumor prognosis was investigated through TCGA database and validated it using the GEO database and analyzed the relationship between IQGAP3 with clinically characteristic tumor TNM staging." (PMID 36164370, 2022). "We further assessed the role of hnRNPC and IQGAP3 in tumor progression by tracing the expression of key epithelial-mesenchymal transition (EMT) markers such as E-cadherin, N-cadherin, and vimentin." (PMID 35355828, 2022). "Another protein regulated by kaempferol is IQ motif containing GTPase-activating protein 3 (IQGAP3), expressed at high levels in tumor breast tissue." (PMID 35457229, 2022). "For further assess tumor prognostic value of IQGAP3, the Kaplan-Meier survival analysis and Cox regression analysis was conducted using TCGA data." (PMID 36164370, 2022). "Using immunohistochemistry, we further assessed the tumor samples for expression of hnRNPC, IQGAP3, and Ki-67." (PMID 35355828, 2022). "High expression of IQGAP3 was correlated significantly with the tumor stage and lymph-node metastasis of different cancer types." (PMID 35274003, 2022). "We identified eight overexpressed and mutated tumor antigens with poor prognostic value of PRAD, including KLHL17, CPT1B, IQGAP3, LIME1, YJEFN3, KIAA1529, MSH5 and CELSR3." (PMID 34872584, 2021). "When comparing the ROC curves of the three tumor markers, IQGAP3 appeared to be the best in its predictive efficacy." (PMID 31223291, 2019). "In this study, we mainly investigated the novel marker IQGAP3 at serum and tumor tissue levels compared with the markers B7-H4 and COX-2 in patients with CRC and in healthy individuals, aiming to evaluate the diagnostic and prognostic value of IQGAP3 for CRC." (PMID 31223291, 2019). "Further analysis of IQGAP3urinary cell-free NAs with respect to tumor invasiveness and grade also yielded ahigh AUC, suggesting that IQGAP3 can discriminate between BC patients andnon-cancer patients with hematuria." (PMID 29581849, 2018). "ROC curve analysis revealed that the AUCs forPicoGreen-adjusted IQGAP3 urinary NAs in BC patients with tumor grades G1, G2, and G3were 0.819, 0.927, and 0.943, respectively, whereas those for RiboGreen-adjustedIQGAP3 were 0.745, 0.881, and 0.886, respectively." (PMID 29581849, 2018). "IQGAP3 urinary NA levels were significantly higher in BC patients at all tumor grades(PicoGreen-adjusted: (all, P<0.001) and RiboGreen-adjusted values: G1(P=0.001), and G2 and G3(P<0.001)) than in normal controls." (PMID 29581849, 2018). "In support of our study, a single study has prospected the role of relative levels of IQGAP1/IQGAP3 in driving epidermal homeostasis towards neoplasia." (PMID 29073199, 2017). "This expression pattern of these two IQGAP isoforms across different cancer types supports the notion that IQGAP2 possibly plays the role of a tumor suppressor gene whereas IQGAP3 is more likely to be an oncogene." (PMID 29073199, 2017). "Oncomine was used to find out differences in mRNA expression of IQGAP2 and IQGAP3, between tumor and normal tissue, in multiple cancers." (PMID 29073199, 2017). "In the present study, we have checked differences in mRNA levels of IQGAP2 and IQGAP3 between tumor and normal tissues in the most commonly occurring human cancers viz." (PMID 29073199, 2017). "An elevated level of IQGAP3 protein was also confirmed in a subset of primary tumours by immunohistochemical staining (n=42, P<0.001, Wilcoxin Signed Ranks Test)." (PMID 26647728, 2015). "Analysis of mRNA expression of 56 RNA sequenced primary tumours and 24 RNA sequenced metastases revealed that IQGAP3 was expressed at a significantly higher level in tumour specimens than adjacent normal tissues." (PMID 26647728, 2015). "A potential role in tumorigenesis was first suggested for IQGAP3 by bioinformatic analyses of IQGAP3 expression in tumor tissue." (PMID 24849319, 2014).
tumor (continued). "Consistent with this concept, overexpression of IQGAP3 enhanced tumor cell growth, migration and invasion, whereas knockdown of IQGAP3 expression displayed opposite effects." (PMID 24849319, 2014). "At the molecular level, IQGAP3 interacts with ERK1 and promotes EGF-induced activation of ERK, which in turn appears to be closely associated with its tumor-promoting activity." (PMID 24849319, 2014). "Overexpression of IQGAP3 promoted tumor cell growth, and migration and invasion, whereas knockdown of IQGAP3 exhibited opposite effects." (PMID 24849319, 2014). "Immunohistochemical staining revealed that relatively normal lung structure was maintained in the IQGAP3 knockdown groups, while it was almost completely destroyed by the multiple tumor nodules in the mock control." (PMID 24849319, 2014). "The CCLE database showed the expression level of IQGAP3 in various tumor cell lines." (PMID 41446602, 2025). "Subsequent studies demonstrated that IQGAP3 mediated tumor progression in a variety of tumors." (PMID 41446602, 2025). "IQGAP3 is crucial for cell cycle, genome stability and tumor stem cell potential." (PMID 38560572, 2024). "In summary, IQGAP3 has the potential to exert a significant impact on tumor progression and immune suppression through its modulation of the immune microenvironment within the tumor milieu." (PMID 38560572, 2024). "Furthermore, IQGAP3 significantly participates in assorted tumor-related signaling pathways, including the EGFR/ERK signaling pathway, ERK1/2 signaling pathway, MEK/ERK, and p38 signaling pathways." (PMID 38560572, 2024). "Further analysis revealed that the risk genes IQGAP3, KRTAP5-1, and KIF4A affected the expression of genes in relation to ICIs in tumor tissues, which may affect the treatment response to ICIs." (PMID 37370891, 2023). "Moreover, the expression of IQGAP3 was positively correlated with infiltration of B cells, macrophages, and dendritic cells, indicating its potential role as a tumor-specific antigen and therapeutic target in PRAD." (PMID 36831467, 2023). "The clinical data showed that positive IQGAP1 expression was associated with larger tumor size, advanced tumor-node-metastasis (TNM) stage, poor relapse-free survival (RFS), and overall survival (OS), and positive IQGAP3 expression was associated with poorer tumor differentiation, RFS, and OS." (PMID 36320006, 2022). "Collectively, these data implied that IQGAP3 may influence antitumor immunity by regulating the composition and immune mechanism in the tumor microenvironment." (PMID 35274003, 2022). "IQGAP3 increased significantly in tumor tissues at different stages." (PMID 36275458, 2022). "In conclusion, the current pan-cancer analysis of IQGAP3 revealed that IQGAP3 was differentially expressed in tumor and normal tissues as well as the correlation of IQGAP3 expression with pathological stage, gene mutation, clinical prognosis, and DNA methylation." (PMID 36164370, 2022). "Therefore, we integrated normal samples from GTEx and databases to match tumor samples from TCGA database to reflect IQGAP3 expression in a more convincing manner." (PMID 36164370, 2022). "Comparing unpaired samples and paired samples, IQGAP3 was highly expressed in most tumor types." (PMID 36275458, 2022). "Thus, IQGAP3 is considered a potential therapeutic target to combat metastasis and tumor progression." (PMID 36559011, 2022). "We wished to further understand the relationship between IQGAP3 and the tumor microenvironment." (PMID 35274003, 2022). "The expression of IQGAP3 is related to TMB and MSI of many tumors, further indicating that IQGAP3 may affect tumor growth and development through immunity." (PMID 36164370, 2022). "Our findings indicated that IQGAP3 could be a good candidate for both early detection biomarkers and novel molecular targeted therapy focusing on suppressing tumor progression." (PMID 32824461, 2020).